PODXL (podocalyxin like)
Diseases named in the same sentence as PODXL in open-access papers (continued):
Sharing a sentence is not in itself a finding about the gene and the disease.
cancer (69 papers, 2012 to 2026). A tumor composed of atypical neoplastic, often pleomorphic cells that invade other tissues. "PODXL-targeting mAbs that selectively recognize cancer-associated glycosylated epitopes, while sparing PODXL expressed on normal tissues, have been developed." (PMID 40843679, 2025). "PODXL codes for a transmembrane glycoprotein that has been previously implicated in endothelial cell adhesion and transvasation during cancer metastasis." (PMID 39448867, 2025). "The ADCC caused by humPcMab-60 against endogenous PODXL-expressing human cancer cell lines was further examined." (PMID 40843679, 2025). "The literature delineates a functional association between the PODXL gene and miRNAs in various cancers." (PMID 38879474, 2024). "Although PODXL has been implicated in the aggressiveness of multiple cancer types, the cellular mechanisms by which PODXL confers this function have remained largely unclear." (PMID 36735782, 2023). "For the development of antibody therapy against PODXL-positive cancers, cancer-specificity is necessary to reduce the risk of adverse effects on normal tissues." (PMID 38203331, 2023). "RUFY1 has been shown to interact with podocalyxin-like (PODXL) protein, an ion exchanger regulatory factor in the membrane protein complex associated with poor prognosis of different cancers." (PMID 35135552, 2022). "PODXL overexpression has been shown to be associated with metastasis in a variety of cancer-tissue types and cancer-cell lines." (PMID 34440856, 2021). "Dysregulation of the cell-surface glycoprotein podocalyxin-like protein (PODXL) plays an important role in promoting cancer-cell motility and is associated with poor prognoses for many malignancy types." (PMID 34440856, 2021). "Loss of PODXL sensitises these cells to these drugs for apoptosis and significantly decreases cancer cell viability." (PMID 34201212, 2021). "Overexpression of podocalyxin (PODXL) is associated with progression, metastasis, and poor outcomes in several cancers." (PMID 33088928, 2020). "In order to obtain more clinical values of PODXL, we investigated the associations between PODXL expression levels and clinical parameters in several cancers." (PMID 32615943, 2020). "As a result, these correlations indicated that the high expressed PODXL was associated with the advanced biological behavior in various cancers." (PMID 32615943, 2020). "Several studies have investigated the associations between the podocalyxin-like protein (PODXL) expression quantity or locations and cancers survival, but the results were far from conclusive." (PMID 32615943, 2020). "For antibody-based therapy to target PODXL-expressing cancers, cancer-specificity is necessary to reduce the risk of adverse effects to normal tissues." (PMID 33088928, 2020). "The contribution of PODXL to human cancer progression has been demonstrated in a variety of cancer cells by gain- and loss-of-function studies, although the underlying mechanisms remain poorly understood." (PMID 32046309, 2020). "Podocalyxin-like 1 (PODXL) was reported to be closely associated with the development of various cancers, yet its functional roles and molecular mechanisms remain vague." (PMID 29748877, 2019). "A meta-analysis on 12 studies revealed that high PODXL expression is significantly associated with worse overall survival in different cancer types." (PMID 31083655, 2019). "PODXL overexpression is associated with the progression, metastasis, and poor outcomes of several cancer types." (PMID 30105309, 2018). "Podocalyxin (PODXL) overexpression is associated with progression, metastasis, and poor outcomes in cancers." (PMID 29854293, 2018). "We demonstrated a novel mechanism underlying PODXL-mediated invasiveness and cancer stemness through regulating TAZ signaling." (PMID 28946619, 2017). "To further gain insight into the role of PODXL in cancer stemness characteristics, we evaluated the effect of PODXL on drug resistance, a hallmark of cancer stemness." (PMID 28946619, 2017).
cancer (continued). "Podocalyxin-like protein 1 (PCLP1) is a selectin-ligand protein in which overexpression has been associated with several aggressive cancers." (PMID 25309871, 2014). "The association of PODXL with hESCs is significant, as a recent paper demonstrated preferential overexpression of hESC markers in poorly differentiated cancers, including GBM." (PMID 24146797, 2013). "Increased podocalyxin (PODXL) expression has been associated with a subset of aggressive types of cancer." (PMID 23596468, 2013). "This review summarises our current knowledge of PODXL in normal tissue function and epithelial cancer, with a particular focus on its underlying roles in cancer metastasis, likely involvement in chemoresistance, and potential use as a diagnostic and prognostic biomarker." (PMID 34201212, 2021). "Moreover, PODXL has been implicated in facilitating immune evasion and resistance of cancer cells to chemotherapy drugs." (PMID 34201212, 2021). "Our meta-analysis showed that PODXL plays a significant role in cancer progression, and high-expressed PODXL could be linked to aggressive biological phenotype and poor prognosis." (PMID 32615943, 2020). "Several studies showed that PODXL is associated with the invasion, migration, epithelial–mesenchymal transition, and metastasis of cancers, and it could be considered an independent prognostic factor." (PMID 33209196, 2020). "Podocalyxin (PODXL), a sialomucin overexpressed in a variety of tumor cell types and associated with their aggressiveness, has been implicated in multiple aspects of cancer progression, although its participation in hematological malignancies remains unexplored." (PMID 32046309, 2020). "PODXL plays an important biological role in the kidney, heart, pancreatic, and breast tissues, and is also a prognostic indicator and a diagnostic marker for several malignant tumors such oral cancer, brain tumors, colorectal cancer, and renal cancer." (PMID 33088928, 2020). "A growing number of studies have implicated PODXL in the development and progression of cancer." (PMID 32046309, 2020). "In conclusion, high expressed level of PODXL was associated with poor OS in 6 types of cancers." (PMID 32615943, 2020). "In addition, both of the expression level and site of PODXL were found to be associated with prognosis of various cancers." (PMID 32615943, 2020). "High expression of PODXL is strongly associated with a poor prognosis of cancer patients." (PMID 32669966, 2020). "Increasing evidences showed that PODXL expression was associated with prognosis in various cancers." (PMID 28881743, 2017). "Although it was reported that PODXL expression might be associated with prognostic outcomes in patients with cancers, the dispute does exist." (PMID 28881743, 2017). "In epithelial cells, PODXL interacts with adaptor proteins that are implicated in actin binding, protein trafficking, and signalling, allowing PODXL to play a pivotal role in many physiological processes including embryonic development, inflammatory responses, and cancer metastasis." (PMID 34201212, 2021). "Our findings identified mutation-dependent changes in drug binding that can guide the development and repurposing of compounds for targeting PODXL-related cancers and improve patient outcomes in PODXL-altered malignancies." (PMID 41718268, 2026). "Using the same strategy, our group established a cancer-specific anti-PODXL mAb, PcMab-60 (IgM, κ), through screening over one hundred hybridoma clones." (PMID 40843679, 2025). "Next, the cell line expressing the highest level of PODXL was used as a model, and cancer spheroid characteristics were investigated by silencing PODXL via CRISPR/Cas9 gene editing." (PMID 38553472, 2024). "Their findings indicated that the downregulation of miR-199a led to an upsurge in PODXL gene expression, which subsequently enhanced the invasive and migratory capabilities of the cancer cells." (PMID 38879474, 2024).
cancer (continued). "PODXL protein, which contributes to cancer progression by interacting with EZR and facilitating cell migration and invasion, was notably overexpressed in Nalm6 cells." (PMID 38879474, 2024). "Another important gene is the PODXL gene, which is upregulated in a wide range of cancers, including malignant brain tumors; breast, prostate, testicular, liver, pancreas, and kidney cancers; and leukemia." (PMID 38879474, 2024). "Podocalyxin (PODXL), an anti-adhesive transmembrane protein, has been reported to promote cancer survival against chemotherapy, however its role in HGSC chemoresistance is unclear." (PMID 38553472, 2024). "In contrast, tissues with high levels of PODXL displayed strong membrane staining; furthermore, when clusters of cancer cells were present, PODXL was stained strongly on the outer layer whereas cells within the centre were negative." (PMID 38553472, 2024). "In this study, utilizing 3D culture of cancer spheroids, we aimed to investigate the functional importance of PODXL in HGSC spheroid including response to chemotherapy drugs." (PMID 38553472, 2024). "Increased PODXL expression can have adverse effects on overall survival, disease-specific survival, and disease-free survival in several cancers." (PMID 38203331, 2023). "PODXL expression alone modestly stratifies outcome in some cancers but becomes a potent predictor of poor outcome when comparing cortical to intracellular levels of PODXL." (PMID 36735782, 2023). "In this study, we developed a cancer-specific anti-PODXL mAb, PcMab-6 (IgG1, kappa), by screening more than one hundred hybridoma clones." (PMID 38203331, 2023). "We developed a PODXL-targeting CasMab in cancer cells by screening more than one hundred clones of anti-PODXL mAbs." (PMID 38203331, 2023). "Elevated PODXL levels are an independent prognostic indicator of disease aggressiveness in several cancers." (PMID 36735782, 2023). "PODXL plays a critical role in cancer development, and PODXL-knockout (KO) mice display lethality before birth." (PMID 38203331, 2023). "The presence of PODXL on the surface of DCs would make this protein a suitable therapeutic target for manipulating the immune response to treat cancer and infectious diseases." (PMID 35711462, 2022). "More importantly, suppression of PODXL substantially reduces cancer cell viability when treated with chemotherapy." (PMID 34201212, 2021). "We particularly examine the mechanisms of PODXL in cancer progression and its potential as a biomarker in the diagnosis, prognosis, and treatment of epithelial cancers." (PMID 34201212, 2021). "Given the association between PODXL expression and the poor prognoses of patients with CRC, we examined the mechanism by which PODXL increases cancer progression in CRC cells." (PMID 34440856, 2021). "On the other hand, PODXL is aberrantly expressed in several cancers, many of which are originated from the epithelium, and PODXL is upregulated in highly aggressive and malignant cancers." (PMID 34201212, 2021). "The function of PODXL in regulating cell adhesion has been attributed to its role in promoting aggressive epithelial cancer phenotypes, as well as enhanced cancer cell growth, invasion, migration, and metastasis." (PMID 34201212, 2021). "As a key regulator of cell morphology, PODXL plays an important role in promoting EMT-like behaviour in cancer cells." (PMID 34201212, 2021). "It has been shown that PODXL is a pluripotent surface marker and enriched in many cancer cells, PODXL positive hematopoietic stem cells can reconstitute myeloid and lymphoid lineages in recipients with lethal radiation." (PMID 34422820, 2021). "For antibody-based therapy to target PODXL-expressing cancers using monoclonal antibodies (mAbs), cancer-specificity is necessary to reduce the risk of adverse effects to normal tissues." (PMID 33088928, 2020).
cancer (continued). "The clinical significance of PODXL in the progression of various cancers has been studied, and it was found as a stem cell marker in the testicular cancer at the first time." (PMID 32615943, 2020). "Combined with the existing results, the expression site of PODXL was a promising markers in predicting the prognosis of cancers." (PMID 32615943, 2020). "Among the eligible 18 studies, there were only 2 researches mentioned the expression location of PODXL and prognosis of cancers, containing 4 cohorts." (PMID 32615943, 2020). "Despite the development of anti-PODXL monoclonal antibodies (mAbs), the efficacy of these treatments against cancers remains to be fully explained." (PMID 33088928, 2020). "Our meta-analysis not only indicated that high expressed PODXL was associated with poor OS, DFS or CSS in patients with cancers, but also showed that membrane expression was correlated with poor OS as well." (PMID 32615943, 2020). "Although PcMab-47 and its modified mAbs are very useful for detecting PODXL in immunohistochemistry, they reacted with both cancer cells and normal cells, including vascular endothelial cells." (PMID 33088928, 2020). "The pooled HR and 95% CI indicated that high-expressed PODXL was significantly related to poor OS in patients with various cancers (HR = 2.33, 95% CI = 1.76–3.09, P < 0.0001) with a significant heterogeneity across these studies (I2 = 63.4%, P = 0.001)." (PMID 32615943, 2020). "In this study, we developed a cancer-specific anti-PODXL mAb, PcMab-60 (IgM, kappa) by immunizing mice with soluble PODXL." (PMID 33088928, 2020). "All of above clinical and experimental evidences are in favor of the oncogenic role of PODXL in the development of human cancers." (PMID 29748877, 2019). "Our current study verified that KLF4, a critical transcriptional factor that had been reported to be involved in the development of different cancers, was the upstream target of PODXL." (PMID 29748877, 2019). "Subsequently, many lines of evidence supported that PODXL occupied a significant role in the development and progression of cancers via acting as an oncogene." (PMID 29748877, 2019). "PcMab-47 reacts with endogenous PODXL-expressing cancer cell lines and normal cells independently of glycosylation in Western blot, flow cytometry, and immunohistochemical analysis." (PMID 29872738, 2018). "We previously produced PcMab-47, a novel anti-PODXL monoclonal antibody (mAb) which reacts with endogenous PODXL-expressing cancer cell lines and normal cells independently of glycosylation in Western blot, flow cytometry, and immunohistochemical analysis." (PMID 29872738, 2018). "In conclusion, it was revealed that high PODXL expression is an unfavorable predictor of OS, DSS and DFS in patients with cancers, and high PODXL expression is a promising prognostic biomarker for cancers, especially for patients in European." (PMID 28881743, 2017). "The anti-PODXL mAb, PcMab-47, reacted with endogenous PODXL-expressing cancer cell lines and normal cells independently of glycosylation in flow cytometry." (PMID 28384052, 2017). "As for the subgroup analysis of sample size, PODXL expression was obviously related to the OS in patients with cancers both when sample size <300(HR=1.88, 95%CI=1.50-2.36, p<0.00001;I2=39%, p=0.13) and≥300(HR=1.62, 95%CI=1.20-2.18, p=0.002; I2=54%, p=0.09)." (PMID 28881743, 2017). "Combining the OS, the high PODXL expression became a promising predictor of prognosis in cancers and should be paid more attention to." (PMID 28881743, 2017). "As for the sample size, the relationship between the PODXL expression and OS was distinct both when sample size≥300 and <300, which further confirmed the prognostic role of PODXL in various cancers." (PMID 28881743, 2017). "Several studies were conducted to explore the prognostic significance of podocalyxin-like protein (PODXL) expression in various cancers, with contradictory." (PMID 28881743, 2017).
cancer (continued). "It was reported that overexpression of TAZ promotes cancer stemness property, and our data showed that PODXL regulates TAZ signaling." (PMID 28946619, 2017). "The prospective or retrospective studies focusing on the prognostic role of PODXL expression in cancers were eligible." (PMID 28881743, 2017). "In view of the controversy, the systematic review and meta-analysis was performed to explore the prognostic role of PODXL expression in various cancers." (PMID 28881743, 2017). "And the results indicated that high PODXL expression was evidently correlated with the shorter DSS in cancers (HR=2.47, 95%CI=1.53-3.99, p=0.0002)." (PMID 28881743, 2017). "It was shown that high PODXL expression predicted shorter DFS when compared with the low PODXL expression in various cancers (HR=2.12, 95%CI=1.58-2.85, p<0.00001)." (PMID 28881743, 2017). "And more studies should be payed attention to the prognostic role of PODXL expression in cancers in Asian." (PMID 28881743, 2017). "In the majority of cases, expression of PODXL was significantly higher in cancer cells compared to normal epithelial cells and was significantly associated with lymph node metastases and high grade tumors." (PMID 27478410, 2016). "Of note, previous studies on colorectal and pancreatic cancer, using a monoclonal anti-PODXL antibody, demonstrated a correlation between cytoplasmic PODXL expression and poor survival." (PMID 27478410, 2016). "From studies with cancer cells it is known that silencing of PODXL reduces migration and interaction with collagen." (PMID 25889587, 2015). "PODXL overexpression has been described in several cancer types including leukemia and breast, colorectal, urothelial bladder, hepatocellular and prostate cancers." (PMID 26053486, 2015). "The clinical significance of PODXL in cancer progression has been investigated in various carcinoma types, first as a stem cell marker in testicular cancer." (PMID 26674770, 2015). "In many cancers, such as renal cell carcinoma, breast, colorectal, urothelial bladder, testicular, and pancreatic cancer PODXL has been reported to be expressed aberrantly and in the first four also to be an independent marker of poor prognosis." (PMID 25004935, 2014). "The role of PODXL in cancer is not fully understood, but it seems to participate in epithelial-mesenchymal transition, and it interacts with different mediators of metastasis." (PMID 25004935, 2014). "Podocalyxin-like protein 1 (PCLP1), a cell-surface sialomucin expressed in a wide range of normal cell as well as in various types of cancer, has been also associated with metastasis." (PMID 25309871, 2014). "The higher expression of PODXL in the RHCC was expected, because these cancers are more poorly differentiated and PODXL expression correlates with differentiation." (PMID 25004863, 2014). "Aberrant expression or allelic variation of PODXL or both occurs in many cancer forms, including renal cell carcinoma, breast, colorectal, testicular, prostate, and pancreatic cancer." (PMID 25004863, 2014). "Similar results to ours has been reported in uterine endometroid carcinoma, where the ectopic apical expression of PODXL in benign uterine endometroid tissue was transformed into cytoplasmic expression in carcinoma." (PMID 25004863, 2014). "Furthermore, in tissues examined here, 29% showed intense and membranous PODXL staining, localising around the outer layer of cancer clusters, which resemble the morphology of budding tumors." (PMID 38553472, 2024). "We further produced the core-fucose-deficient version of humPcMab-6 (humPcMab-6-f) and investigated whether humPcMab-6-f can detect PODXL-expressed cancer cells." (PMID 38203331, 2023). "Both PODXL high and low surface levels occur in parallel subpopulations within cancer cells." (PMID 36735782, 2023).